DKK1 (dickkopf Wnt signaling pathway inhibitor 1)
Diseases named in the same sentence as DKK1 in open-access papers (continued):
Sharing a sentence is not in itself a finding about the gene and the disease.
tumor (continued). "For some tumor resections, less intense DKK1 and PPIB signal was observed." (PMID 33972574, 2021). "Moreover, early blockage of Dkk-1 expression in PCa metastasis prevented tumor development in the bone, suggesting that osteolysis is a critical first step in the progression of PCa bone metastases." (PMID 34437475, 2021). "Emerging evidence has improved our understanding of how DKK1 could promote tumor growth and metastasis through the modulation of signaling pathways in cancer cells." (PMID 34093545, 2021). "Besides confirming previous results, our results also showed the binding affinity of ZBTB38 using ChIP-seq analysis and identified DKK1 as the direct downstream of ZBTB38.expression in mediating its tumor-suppressive role." (PMID 34697293, 2021). "This obvious inconsistency could be interpreted by the rich reservoir of TGF-β in bone matrix and thus the reduced TGF-β of DKK1-expressing tumor cells may be easily compensated." (PMID 34093545, 2021). "DKK1 has been considered to act as either tumor suppressor or promoter." (PMID 34117362, 2021). "Eleven out of 12 tumor resections passed the pre-determined criteria for precision acceptance requiring consistent binning of negative (H-score = 0), low (H-score < 34) and high (H-score ≥ 35) DKK1 signal." (PMID 33972574, 2021). "Dkk1 plays an important role in promoting the apoptosis of tumor cells." (PMID 33639034, 2021). "Furthermore, tumor-derived DKK1 also dictates the OBs fate by inhibiting OBs differentiation and facilitates osteolysis." (PMID 34754042, 2021). "This phenomenon may explain why DKK-1 plays a dual role in tumorigenicity either as a tumor suppressor or promoter." (PMID 34123800, 2021). "DKK1 expression was positively correlated with tumor volume as well as MMP-7 expression." (PMID 34093545, 2021). "We first explored this issue using a set of 6 G/GEJ tumor tissues with a range of DKK1 expression." (PMID 33972574, 2021). "DKK1 has since been shown to increase tumor growth and support an immunosuppressive environment by signaling to MDSCs, and treatment with a DKK1 neutralizing antibody, DKN, 01, was able to mitigate tumor growth by reduced levels of MDSCs and increased entry of effector T cells into the TME." (PMID 32748171, 2020). "The ability of DKK-1 to act as a tumor suppressor or promoter depends on numerous contextual factors (e.g., type of cancer, heterogeneity within the tumor, and tumor microenvironment), indicating that the analysis of this system is complex for in vitro studies." (PMID 32640686, 2020). "Based on its ability to inhibit Wnt, DKK-1 was originally characterized as a tumor suppressor." (PMID 32640686, 2020). "In NSCLC, DKK1 be thought to be involved in tumor cell migration, invasion, and EMT processes, and could be used as an effective diagnostic and prognostic indicator and a potential therapeutic target." (PMID 33287749, 2020). "Conversely, several studies have shown that DKK1 promotes tumor cell proliferation, metastasis, and angiogenesis, which might be mediated by β-catenin-independent signaling." (PMID 33291655, 2020). "On the other hand, our data did not showed any significant correlation between tumor size and all tested markers contrasts with some previous data in literature which showed that DKK-1 protein level correlates significantly with tumor size especially in HCV and/or HBV infected(Supplement-2)." (PMID 32198440, 2020). "DKK1 inhibitors also belong to molecules targeting WNT-signaling, as DKK1, initially characterized as tumor suppressor may also function as tumor promoter." (PMID 32659938, 2020). "HOXD9 was significantly downregulated in tumors with high expression levels of DKK1 and upregulated in tumors compared to controls, indicating that it could be involved in tumor progression through aberrant activation of the Wnt signaling pathway." (PMID 32224864, 2020).
tumor (continued). "By contrast, DKK1 expression was downregulated in renal cell carcinoma and colorectal cancers, indicating that it might function as a tumor suppressor." (PMID 31285694, 2019). "Furthermore, correlation between tumor characteristics of HCC patients and studied markers showed significantly positive correlation between serum DKK1 and tumor size." (PMID 31649806, 2019). "In reverse, when DKK1 was silenced, tumor invasion was significantly reduced." (PMID 31568519, 2019). "To test the hypothesis that DKK1 promotes tumor invasion, we performed gelatin zymography, western blot and qPCR to assess the expression pattern of gelatinases (MMP-2, MMP-9)." (PMID 31568519, 2019). "The effect of DKK1 on cell proliferation and tumor size remains controversial." (PMID 31649806, 2019). "Additional studies have shown tumor stroma-derived DKK1 targeted β-catenin downregulation in myeloid-derived suppressor cells (MDSCs), leading to an accumulation of these cells, a suppressed T cell response, and tumor proliferation." (PMID 31167446, 2019). "Our results showed a significant positive correlation between serum DKK1 and tumor size." (PMID 31649806, 2019). "However, Tung, Mak27 and Shen, Fan24 showed that serum DKK1 was significantly correlated with tumor size." (PMID 31649806, 2019). "This tumor-promoting effect may thus be related to the activation by DKK1 of beta-catenin-independent pathways." (PMID 31568519, 2019). "Finally, knockdown of ERβ resulted in more than 2-fold decrease of DKK1 expression, which is an important inhibitor of the Wnt signaling pathway playing an essential role in tumor invasion and migration." (PMID 31357971, 2019). "Thus, tumor cells that highly secrete DKK1 tend to metastasize to bone, while those with low DKK1 secretion tend to metastasize to the lung." (PMID 31195692, 2019). "The results indicate that DKK1 plays a tumor suppressor role in GC stem cells." (PMID 29720122, 2018). "DKK-1-mediated inhibition of osteoblasts, which contributes to tumor progression and osteolytic metastases, may also play a role in the development of metastases with osteoblastic features." (PMID 30116403, 2018). "DKK1 and ß-catenin expression was evaluated in whole tumor sections by immunohistochemistry." (PMID 29720122, 2018). "Furthermore, elevated DKK-1 expression is an early event in PC and with tumor progression DKK-1 expression declines, particularly in advanced bone metastases." (PMID 30116403, 2018). "Treatment with an anti-Dkk1 antibody, after engraftment of Dkk1 expressing primary MM cells, resulted in a reduced number of osteoclasts, enhanced number of osteoblasts, decreased bone resorption, and a subsequent decrease in tumor burden." (PMID 29776381, 2018). "The downregulation of DKK1 by miR-373-3p is likely to contribute to tumor progression in TSCC." (PMID 28337453, 2017). "Modulation of DKK-1 expression may facilitate development of novel strategies to control tumor angiogenesis and metastasis." (PMID 28938611, 2017). "Additionally, ectopic DKK1 expression impaired the promotive effect of miR-493 on tumor growth of MGC-803 in vivo." (PMID 26799283, 2016). "However, TPA fully rescued either the SR48692- or DKK-1-mediated inhibition on tumor invasion in NTS-treated Hep3Bwt cells." (PMID 27611941, 2016). "To investigate whether the tumor promotive effect of miR-493 was mediated by repressing DKK1 expression, we explored the rescue function of DKK1 in GC cells with different level of miR-493." (PMID 26799283, 2016). "Serum DKK-1 levels diminished to undetectable levels in all treated mice, whether treated immediately or upon development of palpable tumor." (PMID 27049730, 2016).
tumor (continued). "Most importantly, DKK1 down-regulation impaired tumor formation capacity of HCCA cells in vivo." (PMID 27608843, 2016). "One tumor (patient P0027) had a complement of mutations in non-APC components (DKK1/2, CSKN1A1, and AXIN1) of the WNT pathway." (PMID 27245685, 2016). "MiR-493 functioned as tumor promoter in GC via targeting DKK1 expression." (PMID 26799283, 2016). "In this study, we found decreased levels of serum DKK‐1 in most patients after tumor resection." (PMID 26988995, 2016). "Of 205 NSCLCs tumours, 133 were DKK1‐positive (133/205, 64.88%)." (PMID 27240974, 2016). "Vasculogenic mimicry was observed in 28 of 205 NSCLC tumours, while DKK1 was detected in 133 cases." (PMID 27240974, 2016). "Consistently, SR48692, TWS119, and DKK-1 significantly inhibited tumor invasion, in which the cell counts in the Transwell invasion assay declined from 63.33 ± 1.52/104 cells to 32.67 ± 2.51/104 cells, 28.33 ± 1.21/104 cells, and 29.67 ± 5.03/104 cells, respectively (P < 0.001)." (PMID 27611941, 2016). "The apparent paradoxical behavior of DKK-1 as a tumor suppressor and an inducer of chemoresistance may be explained by its distinct roles in the cytoplasm and nucleus and the non-synchronous loss of its expression in both cell compartments." (PMID 25788273, 2015). "DKK1 is a secreted protein with dual anti- and pro-survival functions in different tumor types." (PMID 26353782, 2015). "This prompted us to analyze whether the presence of nuclear DKK-1 within the primary tumor could affect clinical behavior." (PMID 25788273, 2015). "The expression of DKK1 in PC tumor tissues was also evaluated using immunohistochemistry staining." (PMID 26101916, 2015). "Interestingly, DKK2, a homolog of DKK1, increased tumor neovessel formation and perfusion, consequently accelerating tumor growth." (PMID 24091497, 2014). "Consequently, Ad-DKK1 administration significantly prolonged tumor-bearing mouse survival (p < 0.001)." (PMID 24091497, 2014). "Interestingly, tumor vascular density and perfusion were significantly decreased by DKK1 but increased by DKK2." (PMID 24091497, 2014). "There are an increasing number of reports that suggest different mechanisms by which DKK-1 may affect tumour biology." (PMID 25182503, 2014). "Therefore, the function and role of DKK-1 in cancer appears to depend on the cancer cell type and the tumor microenvironment." (PMID 25144498, 2014). "Therefore, the diverse biological functions of DKK-1 in cancer biology appear to depend on the cancer cell types and the tumor niche." (PMID 25144498, 2014). "DKK-1 levels have been described to increase early in disease development, followed by a decrease with tumor progression and bone metastases, which may depict the molecular switch that transitions the osteolytic phenotype to an osteoblastic phenotype." (PMID 24528599, 2014). "Recent studies have examined the cell-free mRNA expression of several genes, including TS, β-catenin, hTERT, CK19, MUC1, CXCR4, Bmi-1, Her-2 and DKK1, these studies have focused on the use of cell-free mRNA for early diagnosis, tumor staging and disease monitoring." (PMID 25496700, 2014). "The role of DKK1 in tumor growth regulation has been suggested in several tumor models." (PMID 24091497, 2014). "While the biological function of linc00467 is completely unknown in the literature, the Wnt antagonist DKK1 is well-known to induce cancer cell apoptosis and function as a tumour suppressor gene." (PMID 24586304, 2014). "Similar pattern of tumor growth was observed in endothelial-specific DKK1 and DKK2 transgenic mice." (PMID 24091497, 2014). "DKK1 was up-regulated in monolayers compared with the original tumor or melanospheres, suggesting that alterations in the gene expression profiles generated by serum might be, at least in part, due to suppression of the Wnt pathway." (PMID 24733089, 2014). "Ad-DKK1 infection significantly reduced tumor vessel density (58 % of Ad-Mock controls)." (PMID 24091497, 2014).
tumor (continued). "Likewise, expression of IL-1β and inhibitors of Wnt signaling, such as DKK-1, in tumor cells have been reported to be involved in malignant osteolysis through both an activation of osteoclastogenesis and an inhibition of bone formation." (PMID 25490771, 2014). "Tumor size was significantly reduced in DKK1 Tg mice versus wild-type controls (2,590 ± 463 vs. 3,368 ± 856 mm3, respectively; p < 0.001), which correlated to increased survival in DKK1 Tg mice (p < 0.001)." (PMID 24091497, 2014). "DKK1 mediates tumor suppression in some cancer cells by blocking the Wnt/β-catenin pathway." (PMID 23922913, 2013). "DKK1 is expressed in numerous human cancers; it might play diverse biological roles in tumor cells depending on the cell type involved." (PMID 24391982, 2013). "Both gain- and loss-of-function studies showed that DKK1 did not influence the tumor cell proliferation and colony formation, while dramatically promoted HCC cell migration and invasion." (PMID 24325363, 2013). "Moreover, the increased expression of DKK1 closely correlates with multiple tumor nodes, high Edmondson-Steiner grade and vein invasion, as well as poor overall and disease-free survival of HCC." (PMID 24325363, 2013). "Next, we asked for the functional role of DKK1 in tumor cells." (PMID 24325363, 2013). "Indeed, tumor cells derived from DKK1-transfectants displayed a higher ability of migration, compared with that derived from Vector or nontransfected cells." (PMID 24325363, 2013). "First, we examined the role of DKK1 in tumor cell migration by using wound scratch assay." (PMID 24325363, 2013). "The results indicated that the upregulation of β-catenin and MMP14 the knockdown of DKK1 may result in the elevated activation of the Wnt signaling pathway and downstream signaling events involved in tumor migration and invasion." (PMID 24137406, 2013). "Few studies have analyzed the biology of DKK1 function in tumor invasion and migration." (PMID 24137406, 2013). "In addition, the DKK1 protein was undetectable in MM cell lines, which represent the ultimate, microenvironment independent, phase of MM tumor progression and are almost invariably derived from extramedullary MMs." (PMID 22363428, 2012). "Upregulation of DKK1, a Wnt/β-catenin pathway antagonist, may promote tumour invasiveness though the exact mechanism is yet unknown." (PMID 22925330, 2012). "Give our current finding that DKK1 inhibits autocrine canonical Wnt signaling in MM cells, inhibition of DKK1 could hyperactivate the Wnt pathway and thereby promote tumor growth, especially at extramedullary sites." (PMID 22363428, 2012). "DKK1 staining was mainly observed in the cytoplasm of tumor cells." (PMID 22649545, 2012). "Together, these studies suggest that MM bone disease and tumor growth are interdependent, at least at the intramedullary stage, and that increased bone formation as a consequence of neutralization of DKK1, may also control MM growth.." (PMID 22363428, 2012). "Although blocking DKK1 inhibits osteolytic bone disease in vivo, targeting DKK1 in MM patients could enhance Wnt pathway activity in MM plasma cells, which might increase the metastatic potential and extramedullary growth of the tumor." (PMID 22363428, 2012). "Therefore, we simulated the combined multi-scale mathematical model to study the role of Dkk1 in BC-SC regulation, in order to predict the conditions, within the tumor environment, which divert BC-SCs from proliferation." (PMID 21915302, 2011). "Cells transfected with DKK-1 had fewer and smaller tumor foci vs. GFP control." (PMID 21317455, 2010). "Though in the same tumor-stroma milieu, DKK-1 produced by MM cells could inhibit the Wnt signaling in osteoblast progenitors, but failed to block the Wnt signal transduction in MM cells." (PMID 20846389, 2010).
tumor (continued). "In the same tumor-stroma milieu, DKK-1 produced by MM cells could inhibit the Wnt signaling in osteoblasts and their progenitors, but failed to block the Wnt signal transduction in MM cells." (PMID 20846389, 2010). "The function of DKK-1 in tumor progression has been shown to be complicated and even controversial." (PMID 20920327, 2010). "Nine tumours displayed low ASCL1/high DKK1 and six tumours high ASCL1/low DKK1 expression." (PMID 19744316, 2009). "However, the expression of DKK1 is elevated in some tumor cells including myeloma cells, hepatoblastoma cells and Wilm's tumor cells." (PMID 19247449, 2009). "Given evidence that ectopic expression of DKK1 suppresses features of transformation in tumor cells, DKK1 might inhibit tumorigenicity." (PMID 19247449, 2009). "In some tumor types, Wnt antagonists including DKK1 act as tumor suppressors." (PMID 19247449, 2009). "Inverse relation of ASCL1 to DKK1 expression was observed for 15 out of 22 tumours (68%)." (PMID 19744316, 2009). "On the other hand, methylation of DKK1 was detected in only 15 (19%) of the 78 tumours." (PMID 18283316, 2008). "Employing in vitro assays, we examined the possibility that immunodepletion of Dkk-1 or administration of GSK3β inhibitors could represent an adjunct therapy for this disease by improving osteogenic tissue repair adjacent to the tumour." (PMID 17987039, 2007). "In spite of the hosts' response to the implanted cells, human Dkk-1 could be detected in the blood of the recipient mice, demonstrating that tumour-derived Dkk-1 escapes into the blood stream." (PMID 17987039, 2007). "Furthermore, the in vivo data demonstrate that the level of Dkk-1 detectable in blood is proportional to the number of surviving OS cells in the tumour." (PMID 17987039, 2007). "The presence of Wnt signalling inhibitors such as Dkk-1 can disrupt the repair of bone and its secretion by tumours into the bone can lead to irreparable damage to the tissue." (PMID 17987039, 2007). "Although the data presented here demonstrate that Dkk-1 may contribute to OS pathogenesis by preventing repair of the surrounding osteoid as the tumour expands, Dkk-1 may act in an autocrine manner on the tumour cells too." (PMID 17987039, 2007). "The mechanism(s) by which the internally truncated LRP5 receptor activates β-catenin signaling in tumor cells remains to be elucidated, but may involve impaired inhibition by DKK1." (PMID 18044981, 2007). "Since tumour-derived Dkk-1 was present in the blood of mice at levels proportional to the number of surviving tumour cells, Dkk-1 may serve as a powerful and noninvasive tool for the evaluation of patients with OS." (PMID 17987039, 2007). "We next evaluated if DKK1 was expressed in tumours of other origins." (PMID 17245340, 2007). "Furthermore, the expression of Dkk-1 by the OS cells at the periphery of the tumour probably contributes to its expansion by inhibiting repair of the surrounding bone." (PMID 17987039, 2007). "Because Dkk-1 could not be detected in the bone marrow of naive animals, this suggests that MDA-B02 tumour cells were the major source of Dkk-1 in the bone marrow." (PMID 17876334, 2007). "The host microenvironment in the patients may be more readily affected by the tumour than the surrounding mouse tissue accounting for the reduced levels of Dkk-1 in the mouse blood when compared to the human blood." (PMID 17987039, 2007). "LRP5 gene fusion with UBE3C results in the loss of the DKK-1 inhibitory domain; in a study of head and neck cancers, this fusion was found to stimulate Wnt/β-catenin signaling and upregulate MYC, CCND1, TCF4, and LEF13 expression, resulting in tumor cell proliferation." (PMID 40940800, 2025). "However, subsequent studies have shown that DKK1 also contributes to tumor progression." (PMID 40025612, 2025).